COL6A3 (collagen type VI alpha 3 chain)
Diseases named in the same sentence as COL6A3 in open-access papers (continued):
Sharing a sentence is not in itself a finding about the gene and the disease.
gastric cancer (21 papers, 2014 to 2025). A primary or metastatic malignant neoplasm involving the stomach. "circCOL6A3/miR-3064-5p/COL6A3 axis can regulate the malignant behaviors of gastric cancer cells and so on." (PMID 38682035, 2024). "At the same time that we were doing this, Xiaoli Sun team study showed that over-expressed circCOL6A3 promoted cell proliferation, migration, and apoptosis of gastric cancer through the rescission of miR-3064-5p-induced inhibitory effect on COL6A3." (PMID 34595992, 2021). "The literature showed that in vitro experiments, the over-expressed circCOL6A3_030 promoted the proliferation, migration, and apoptosis of gastric cancer cells by relieving the inhibition of mir-3064-5p on COL6A3." (PMID 34595992, 2021). "COL6A3 gene silencing inhibits gastric cancer cell proliferation, migration, and invasion while promoting apoptosis through the PI3K-Akt signaling pathway." (PMID 33542901, 2020). "COL6A3 and KLK7 in CRCs, SHC3 in hepatocellular carcinomas, and TREM2 in gastric cancers and renal cell carcinomas are associated with tumor growth." (PMID 33037736, 2020). "circ6401, a circRNA that was previously reported to participate in gastric cancer development by regulating miR-3064-5p-induced inhibitory effect on COL6A3, has been rarely reported in MSCs and, thus, needed to be validated." (PMID 33261656, 2020). "COL6A3 gene silencing inhibits gastric cancer cell proliferation, migration, and invasion and promotes apoptosis through the PI3K-Akt signalling pathways." (PMID 31895688, 2020). "Association between the expression of circulating COL6A3, SERPINH1 and PLEKHG1 in gastric cancer and clinicopathologic characteristics." (PMID 31249732, 2019). "There are few reports on gastric cancer at present, and only one literature suggests that COL6A3 may be an oncogene of human gastric cancer, and the antagonism of COL6A3 may be an effective method to treat gastric cancer." (PMID 35574353, 2022). "Reports on gastric cancer and colorectal cancer also showed high expression of COL6A3, but interestingly in our study, COL6A3 has shown lower expression and this downregulation might be due to mucinous nature of the cervical tissue." (PMID 33829064, 2021). "Another study that performed a microarray meta-analysis found that type VI collagen (COL6A3) was regularly overexpressed in gastric cancer cells and suggested that gene could act as an oncogene." (PMID 34512204, 2021). "It has been observed that COL6A3 acts as an oncogene in cancer and that the antagonism of COL6A3 could be developed as an effective therapeutic treatment for gastric cancer." (PMID 31895688, 2020). "The overexpression of COL6A3 has been demonstrated to correlate with high-grade ovarian cancer and contributes to cisplatin resistance; however, its role in human gastric cancer (GC) remains unclear." (PMID 24765172, 2014). "The expression of COL1A2, COL6A3, and THBS2 genes leads to the development, migration, and invasion of gastric cancer cells, and reduces apoptosis through the PI3K-Akt pathway." (PMID 37361568, 2023). "Similar results were also found in gastric cancer, in which the upregulated genes were COL1A2 and COL6A3 or COL6A3, COL3A1, and COL1A1." (PMID 38069077, 2023). "Previous article has verified silence of COL6A3 and COL1A2 can inhibit tumor cell proliferation, migration, and invasion in the gastric cancer." (PMID 33928021, 2021). "Prior studies have implicated these TRIP13 targets in the progression of various cancers, including COL6A3 and KLK7 in CRCs, SHC3 in hepatocellular carcinomas, and TREM2 in gastric cancers and renal cell carcinomas." (PMID 33037736, 2020).
Bethlem myopathy (18 papers, 2012 to 2024). A usually autosomal dominant inherited movement disorder caused by mutations in the COL6A1, COL6A2, and COL6A3 genes. "For example, COL6A2 and COL6A3 jointly encode type VI collagen, and their mutation will lead to an autosomal dominant disease, namely Bethlem myopathy." (PMID 35872873, 2022). "Four families had mutations in COL6A2 and COL6A3, typically associated with Bethlem myopathy, but recently also found in LGMD-like cases." (PMID 29970176, 2018). "COL6A3 mutations in particular are associated with congenital muscular disorders such as Ullrich muscular dystrophy and Bethlem myopathy which are characterized by progressive skeletal muscle weakness." (PMID 26179878, 2015). "Bethlem myopathy is almost exclusively caused by dominant COL6A1, COL6A2, or COL6A3 mutations, whereas UCMD occurs as a result of both recessive and dominant mutations." (PMID 28918041, 2017). "Some heterozygous premature termination codon (PTC) mutations in COL6A1 cause Bethlem myopathy but they are non-pathogenic when they occur in COL6A2/COL6A3." (PMID 31387942, 2019). "Even though phenotypic overlap between patients with COL12A1‐related myopathy and patients with Bethlem myopathy, a form of COL6‐related dystrophy due to mutations in collagen VI genes (COL6A1, COL6A2, or COL6A3) has been noted, several features help distinguish these disorders." (PMID 31509352, 2019).
colorectal cancer (18 papers, 2015 to 2026). A primary or metastatic malignant neoplasm that affects the colon or rectum. "In a previous study, COL6A3 has been shown to be a potential plasma marker of colorectal cancer and is associated with tumor metastasis." (PMID 31249732, 2019). "Expression of COL6A3 is required for the survival, migration, and invasion of many cancer cell lines, including breast, bladder, liver, and colorectal cancers." (PMID 41228242, 2025). "In colorectal cancer, Cas9-mediated knockout of COL6A3 reduced cell proliferation, migration, and induced early apoptosis." (PMID 41228242, 2025). "While COL6A3 expression has been explored as a prognostic biomarker in colorectal cancer, less is known about the role of COL6A3 in breast cancer." (PMID 36901727, 2023). "In accordance with the data from The Cancer GenomeAtlas Program(TCGA), COL6A3 expression levels were higher in colorectal cancer tissues compared to the normal tissues." (PMID 35936754, 2022). "Hsa_circ_0006401 encodes a novel 198-aa functional microprotein that reduces the mRNA and protein levels of host genes COL6A3 and TGFβ1 and promotes colorectal cancer proliferation and metastasis by protecting COL6A3 mRNA from degradation." (PMID 35936754, 2022). "In our study, we found COL6A3 is highly expressed in colon cancer, and its expression correlate with poor survival outcomes, which further emphasized the crucial role of COL6A3 as a tumor promoter in colorectal carcinoma." (PMID 33947841, 2021). "Another study found that COL6A3 was a potential prognosis marker of colorectal cancer, which was upregulated in cancer tissues." (PMID 31627190, 2019). "COL6A3 protein and mRNA are significantly upregulated not only in colorectal cancer cells but also in the stromal cells of tumor lesions, which promote tumor growth by modulating Hippo and Wnt signaling." (PMID 28415608, 2017). "The upregulation of COL6A3 protein and mRNA in the cancer stroma predicts poor outcomes in patients with colorectal cancer." (PMID 28415608, 2017). "Furthermore, it establishes role of TRIP13 in colorectal cancer metastasis and identifies COL6A3, TREM2, SHC3, and KLK7 as its downstream targets." (PMID 33037736, 2020). "In addition, COL6A3 played the clinical relevance in the development of colorectal cancer validated by silico analysis of cell type-specific gene expression and COL6A3 knockout experiments." (PMID 31286980, 2019). "Indeed, oncomine analyses and tissue-microarray immunohistochemistry showed overexpression of COL6A3 in colorectal carcinomas that was significantly and directly correlated with Dukes stage, T stage, stage, recurrence and smoking status and then with a poor prognosis." (PMID 27874091, 2016).
breast carcinoma (17 papers, 2013 to 2025). "High expression of COL6A3 is correlated with increased relapse-free survival (p = 0.031) in HER2+ breast cancer patients." (PMID 36901727, 2023). "There is a trend of decreased COL6A3 expression with increasing tumor stage in breast cancer patients, which suggests a propensity for invasion and metastasis in these tumors." (PMID 36901727, 2023). "Previous studies have shown that overexpression of COL6A3 promotes cisplatin resistance in ovarian cancer cells and breast cancer cells." (PMID 36167487, 2022). "Previously, upregulation of COL6A3 has been reported in platinum-resistant OC cells in vitro, and inhibition of the cleaved product of COL6A3, endotrophin, can sensitize cisplatin-resistant breast cancer cells." (PMID 34162871, 2021). "An alternative mRNA transcript of the other collagen-isoform gene, COL6A3, was also reported to be upregulated in almost all breast cancer samples although, again, the significance of this finding for TNBC has not been explored." (PMID 31139569, 2019). "COL6A3 is the largest of these three chains and the cleavage of the C5 domain, also called endotrophin, has a crucial role in breast cancer development, and it is a ligand for ANTXR1-receptor, which is a putative biomarker for breast CSC." (PMID 29719832, 2018). "The goal of this study was to elucidate the roles of endotrophin, a cleavage product of COL6A3, in cisplatin resistance and elaborate further to see if endotrophin modulates the beneficial effects of TZDs in cisplatin therapeutics in breast cancer." (PMID 23629957, 2013). "Notably, COL6A3 and PRRX1 have been shown to confer resistance to chemotherapeutic agents like cisplatin, and circulating COL6A3 has been proposed as a prognostic biomarker for colorectal and breast cancers." (PMID 39920655, 2025). "Much like in ovarian cancer, COL6A3 is highly upregulated in cisplatin-resistant mammary tumors." (PMID 41228242, 2025). "Risk analysis based on pSAR values of splicing events showed that splicing events occurring on TNC and COL6A3 could be used to evaluate breast cancer prognosis." (PMID 38783078, 2024). "Conclusively, eight RBPs such as RBMS3 and AS of TNC and COL6A3 could be used as predictors of breast cancer prognosis." (PMID 38783078, 2024). "Although Collagen Alpha-3 (VI) COL6A3 was shown to enhance brain metastasis in breast cancer patients, COL6A3 was upregulated in NRP-1 KO cells which showed less metastatic lesions to the lungs; future gain and loss of function studies will reveal more information about the actual role of this gene." (PMID 37175499, 2023). "Further, increased expression of COL6A3 in breast cancer after chemotherapy may predict for responsiveness to chemotherapy." (PMID 36901727, 2023). "Similarly, Col6a3 is up-regulated in the stroma of colon tumours, and promotes the development of hyperplastic foci and primary tumour growth in breast cancer models by activating pro-survival and proliferation pathways involving, as seen here, β-catenin." (PMID 24498316, 2014). "By analysing DERBPs and differential AS in breast cancer tissues in TCGA, it was found that the expression levels of RBPs such as RBMS3 and the pSAR values of AS occurring on TNC and COL6A3 were significantly correlated with the prognosis of patients." (PMID 38783078, 2024). "OPN, IL-8, and COL6A3 exposure upregulated EMT-related genes and COL6A3 supported breast cancer cell drug resistance." (PMID 29719832, 2018). "By further analysing above EMT-related RBPs and AS in breast cancer tissues in TCGA, it was found that the expression levels of ADAT2, C2orf15, SRP72, PAICS, RBMS3, APOBEC3G, NOA1, ACO1 and the AS of TNC and COL6A3 were significantly correlated with the prognosis of breast cancer patients." (PMID 38783078, 2024).
breast carcinoma (continued). "By establishing the correlation network of differential RBPs and differential AS events, we found that RBM47, PCBP3, FRG1, SRP72, RBMS3 and other RBPs may regulate the AS of ITGA6, ADGRE5, TNC, COL6A3 and other cell adhesion genes, which may affect the EMT process of breast cancer cells." (PMID 38783078, 2024). "Additionally, the COL6A3 fragment endotrophin (ETP) has been suggested to enhance EMT in cancer cells, although it is not responsible for migration effects in breast cancer cells." (PMID 36546396, 2022).
muscular dystrophy (16 papers, 2014 to 2025). Muscular dystrophy (MD) refers to a group of more than 30 genetic diseases characterized by progressive weakness and degeneration of the skeletal muscles that control movement. "The COL6A3 encodes Collagen type VI alpha 3 chain protein and deleterious variants are mainly associated with muscular dystrophy following both AD and AR patterns of inheritance." (PMID 37035729, 2023). "The collagen type VI alpha 3 (COL6A3) gene, encoding the collagen alpha-3(VI) chain, is recognized as being associated with muscular dystrophy." (PMID 33964895, 2021). "In context of mammalian muscular dystrophies involving COL6A3 mutations, its expression is usually deficient." (PMID 32670085, 2020). "Because gene mutations in COL6A1, COL6A2 and COL6A3 have been shown to result in muscular dystrophy, which indicated that collagen VI is particularly necessary for the vitality of skeletal muscle." (PMID 31286980, 2019). "Collagen VI–related disorders (COL6-RDs) are a group of rare muscular dystrophies caused by pathogenic variants in collagen VI genes (COL6A1, COL6A2, and COL6A3)." (PMID 40309777, 2025). "Among other muscular dystrophies, 20 of 24 patients (83.3%) had variants in LAMA2 (n = 6), LMNA (n = 5), COL6A1 (n = 4), CHKB (n = 2), COL6A2 (n = 2), and COL6A3 (n = 1)." (PMID 40494860, 2025). "Multiple genes with high loading in LF1 relate to muscular dystrophy with the Dmd gene ranking in top 100 genes, and all 3 Col6a genes (Col6a1, Col6a2 and Col6a3 genes) responsible for Ulrich muscular dystrophy are present in the top 40 genes in LF1." (PMID 37000843, 2023). "The presence of fibrosis, essentially composed of collagen, a characteristic of all muscular dystrophies, is present in UCMD patient biopsies and was also described in the Col6a3 deficient mouse model." (PMID 26221953, 2015). "Here, we reported four patients with PD harboring potentially pathogenic biallelic variants in COL6A3, and all the patients showed typical manifestations of PD without dystonia or muscular dystrophy." (PMID 37304079, 2023). "It is hypothesized that COL6A3 accelerates cell anchoring and signaling through its interaction with integrin and disruption of this gene results in muscular dystrophy." (PMID 24765172, 2014).
Insulin resistance (15 papers, 2015 to 2026). Increased resistance towards insulin, that is, diminished effectiveness of insulin in reducing blood glucose levels. "Collagen Type VI Alpha 3 (COL6A3) is associated with insulin resistance and adipose tissue inflammation." (PMID 35692390, 2022). "Interestingly, COL6A3 is also associated with insulin resistance, pointing to its significant role in metabolic diseases and wound healing challenges after long-term space missions." (PMID 40130165, 2025). "The question of whether COL6A3 upregulation is a primary cause of insulin resistance leading to microgravity/disuse osteoporosis deserves further investigation." (PMID 40130165, 2025). "Studies have shown that the expression of COL6A3 mRNA in adipocytes is positively correlated with body mass index and insulin resistance." (PMID 38689297, 2024). "COL6A3 acts directly through macrophage accumulation, leading to inflammation and insulin resistance, and possibly contributing to a worse metabolic profile." (PMID 35068329, 2022). "Not only that, inhibiting COL6A3 expression was related to insulin resistance and adipose tissue inflammation via suppression of the induction of monocyte chemoattractant protein (MCP1)." (PMID 31286980, 2019). "Furthermore, the C-terminal portion of COL6A3 collagen protein, known as endotrophin, has been shown to trigger adipose tissue fibrosis, inflammation, and insulin resistance in mice." (PMID 34385484, 2021). "Our RNA-seq data showed that Col6a3 mRNA level was decreased in the iWAT of AAV-Notum treated mice, which might contribute to improved insulin resistance." (PMID 34385484, 2021).
Dystonia (12 papers, 2016 to 2025). An abnormally increased muscular tone that causes fixed abnormal postures. "Our findings indicated that rare variants in several dystonia-related genes are suggestively associated with PD, and taken together, the role of COL6A3 and TH genes in PD is highlighted." (PMID 37304079, 2023). "Mutations in the collagen type VI alpha 3 (COL6A3) gene were recently identified as a cause of isolated dystonia." (PMID 33964895, 2021). "Further studies on the function and mechanism of COL6A3 and other dystonia-related genes are needed to unravel the complexity of the association between PD and dystonia." (PMID 33964895, 2021). "Since PD and dystonia are closely related disorders with shared clinical and genetic characteristics, we explored the association between COL6A3 and PD in a Chinese cohort." (PMID 33964895, 2021). "The recessive COL6A3 mutations (p.R3043H and p.P3082R) can cause neurological disorder early-onset isolated dystonia." (PMID 31286980, 2019). "Two other recessively inherited isolated dystonias have also been described arising from mutation of DYT2 (HPCA) or DYT27 (COL6A3)." (PMID 29110692, 2017). "None of the variants were located in previously reported hotspots for mutation in dystonia (exons 41 and 42), indicating variants in specific regions of COL6A3 may have an association with PD." (PMID 37304079, 2023). "Recent studies revealed that compound heterozygous mutations in collagen type VI alpha-3 gene COL6A3 may cause recessive isolated dystonia (DYT)-27." (PMID 37082441, 2023). "In addition, mutations in the COL6A3 gene were found in patients affected by recessive isolated dystonia, a human brain disorder." (PMID 27060109, 2016). "Thus, they concluded that variants in COL6A3 may cause dystonia by affecting the extracellular matrix in the central nervous system, and that exons 41 and 42 are hotspots for mutation." (PMID 33964895, 2021). "In situ hybridization in adult mouse brain sections showed that neurons, including those located in the motor areas and known to be related to dystonia, express the Col6a3 gene." (PMID 29728408, 2018). "Intriguingly, a recent study used morpholino-mediated disruption of col6a3 exon 42 in zebrafish embryos to corroborate data collected from human patients affected by dystonia." (PMID 29728408, 2018). "A previous study conducted in China reported a PD patient without dystonia symptoms carrying compound heterozygous variants in COL6A3 gene." (PMID 37304079, 2023). "However, to the best of our knowledge, at present, only seven cases of compound heterozygous COL6A3 in dystonia were reported in Caucasian and Indian patients." (PMID 37082441, 2023). "Therefore, our findings may expand the spectrum of the COL6A3 genotype in the development of isolated dystonia." (PMID 37082441, 2023). "Whether these compound heterozygous mutations or other variants in COL6A3 were present in Chinese dystonia patients have not been reported so far." (PMID 37082441, 2023). "Moreover, as a fact, only a few cases of compound heterozygous COL6A3 in dystonia were reported to date, and more new cases in the future should be reported to demonstrate the relationship between compound heterozygous COL6A3 and the occurrence of dystonia." (PMID 37082441, 2023). "However, whether COL6A3 mutations are associated with Chinese patients with isolated dystonia is not yet reported." (PMID 37082441, 2023). "However, since the patient currently shows no symptoms of dystonia, we assume variants in some region of COL6A3 may have an association with PD." (PMID 33964895, 2021). "Notably, dystonia or Parkinson-related proteins are altered in the XDP MSNs proteome, including ATP1A3, COL6A3, GBA, GIGF2, HTRA2, MAP2, SNCA, and TORAIP2." (PMID 38042508, 2024).